SMAD3 (SMAD family member 3)
Diseases named in the same sentence as SMAD3 in open-access papers (continued):
Sharing a sentence is not in itself a finding about the gene and the disease.
tumor (continued). "We next hypothesized that loss of tumor-suppressive activity is caused by changes in the spectrum of TGF-β/Smad3 target genes with increasing tumor progression." (PMID 24890385, 2014). "Thus we reasoned that events downstream of Smad3 activation are primarily responsible for the loss of tumor suppression in M4 cells." (PMID 24890385, 2014). "Although most Smad3−/− mice survived to endpoint, disease signs consistent with tumor development (diarrhea, hunched posture, blood in feces, weight loss, palpable mass in abdomen) necessitated euthanasia of 5/17 Smad3−/− mice (between 19.4 to 25.6 weeks) prior to the study endpoint of 27 weeks." (PMID 24244446, 2013). "The current results revealed that aberrant TGF-β1 was associated with Smad2 and Smad7 expression in tumor tissues, and that direct coculture GC cells with PBMCs could promote the expression of Smad2 and Smad3." (PMID 23342108, 2013). "In addition, we analyzed the relationship between SMAD3 gene expression and tumor mutation load." (PMID 38514720, 2024). "In addition, SMAD3 drives lung carcinogenesis by affecting tumour-associated fibroblasts (TAFs)." (PMID 37685308, 2023). "In addition, SMAD3 drives lung carcinogenesis by affecting tumour-associated fibroblasts." (PMID 37685308, 2023). "Furthermore, inhibition of CD4+ Foxp3+ Treg cells could be another mechanism associated with enhanced NK cell immunity in the tumour-bearing Smad3−/− mice." (PMID 28262747, 2017). "Thus it is likely that enhancement of NK cell-mediated anticancer immunity may be associated with inhibition of Treg cells in the Smad3−/− tumour microenvironment." (PMID 28262747, 2017). "Interestingly, SMAD3 deficiency promotes tumor formation in the distal colon of Apcmin/+ mice." (PMID 26101583, 2015). "However, basally high levels of linker phosphorylation of Smad3 were already evident in the malignant M3 cells, which nevertheless still retain their tumor suppressive responses to TGF-β, so loss of tumor suppression in M4 cells cannot be due to de novo Smad3 linker phosphorylation." (PMID 24890385, 2014). "This analysis revealed associations with multiple proteins, including SMAD3, RNF14, PPM1A, and OPHN1, implicating PCDH1 in signaling cascades relevant to tumor progression and stemness regulation." (PMID 41602375, 2026). "Interfering with TGF-β signaling on various levels, including inhibition of TGF-β receptor kinase with SM16 or inhibition of Smad3 with its inhibitor SIS3 promoted neutrophil anti-tumor polarization." (PMID 40050933, 2025). "In valve interstitial cells, tumor stemness index (TSI) alleviates aortic valve calcification by inhibiting the TGF-β/Smad3 pathway by downregulating osteoblastic differentiation." (PMID 40354352, 2025). "In GBM, expression of THBS1 is transcriptionally regulated via the TGF-β/SMAD3 axis and enriched at the invasive tumor margins." (PMID 40885689, 2025). "This included for example for bendamustine EIF3M involved in cell proliferation, cell cycle progression and cell death, SMAD3 involved in epithelial-to-mesenchymal transition, tumor suppressor and metastasis formation, and UBXN1 influencing EGFR signaling." (PMID 41146244, 2025). "Although the difference was not statistically significant, there was a trend toward an increased frequency of p-Smad3-positive tumor cells in the Anti-PD-1+TR group compared to the Chemo+TR group (p = 0.085)." (PMID 40801643, 2025). "Elevated NAT10 expression stabilizes SMAD3 mRNA via this modification, facilitating tumor progression and contributing to the activation of the TGF‐β signaling pathway." (PMID 41476650, 2025). "SMAD3 overexpression fully rescued the tumorigenic capacity of NAT10‐knockdown cells in the mouse xenograft model, with a marked increase in both tumor volume and weight in the SMAD3‐rescue group." (PMID 41476650, 2025). "We analyzed the expression level of HLA class I on tumor cells in relation to p-Smad3 expression levels using serial tissue sections." (PMID 40801643, 2025).
tumor (continued). "These correlations underscore the potential role of SMAD3 in orchestrating tumor–stromal interactions and immune recruitment processes." (PMID 40361382, 2025). "TGF-β1 significantly promotes the proliferation, migration, and invasion of tumor cells by activating the Smad3 signaling pathway." (PMID 39940962, 2025). "Whereas, epithelial marker, E-cadherin, declined with tumor grading, sharply contrasting those of p-Smad3 and USP9X." (PMID 40246814, 2025). "In our study, we observed dynamic chromatin alterations in the tumor microenvironment related to the activation levels of the SMAD3 signaling pathway or its DNA‐binding ability, regulated by the NSUN5–SMAD3 axis." (PMID 39531371, 2025). "Subsequently, tumor formation experiments in nude mice revealed that NSUN5 KO significantly reduced SMAD3 and p‐SMAD3 levels in tumors, accompanied by an increase in E‐cadherin (an epithelial marker) and a decrease in vimentin (a mesenchymal marker)." (PMID 39531371, 2025). "RUNX3 plays a crucial role in TGF-β signaling via binding with Smad family including Smad2, Smad3 and Smad4 and tumor suppression pathways." (PMID 40354349, 2025). "Consistent with the results for total MDSC, transcripts of Smad3 suggested a significant decrease in tumor MO-MDSC compared to wild-type mice-derived CD11b+Ly6C+ cells and pMΦ, which prompted us to investigate the underlying mechanisms." (PMID 41360769, 2025). "The reduced expression levels of TGF-β1 and p-Smad3 proteins further confirmed that siTGF-β1@ILP effectively inhibited tumor cell proliferation and migration by suppressing the TGF-β/Smad signaling pathway, thereby exerting significant antitumor effects." (PMID 39940962, 2025). "Overall, these findings highlight the importance of Mettl3-mediated m6A modification at the 3’UTR of Smad3 mRNA in its low expression in tumor MO-MDSC, due to impaired mRNA stability by Ythdf2 recognition." (PMID 41360769, 2025). "Compared to the group with <5% of p-Smad3-positive tumor cells (30 fields), the group with ≥5% (30 fields) showed significantly downregulated HLA class I expression on tumor cells (p = 0.024)." (PMID 40801643, 2025). "Our results suggest that NAT10 regulates anoikis resistance in HCC cells by modulating key genes, including SMAD3, thus facilitating tumor cell EMT and enhancing malignant progression." (PMID 41476650, 2025). "When the TGF-β signaling pathway is activated, SMAD3 is phosphorylated and translocated to the nucleus, where it regulates the expression of genes related to tumor metastasis in conjunction with other transcription factors." (PMID 40066091, 2025). "Different studies have confirmed that transforming growth factor‐beta (TGF‐β) inhibits telomerase gene activity via mothers against decapentaplegic homolog 3 (Smad3) in tumor cells and cultured mouse fibroblasts." (PMID 40629711, 2025). "Concurrently, Smad3—a tumor suppressor that enforces G1 arrest—is functionally inactivated in resistance models through CDK2-cyclin E-mediated phosphorylation, bypassing Rb-E2F suppression to restore cell cycle progression." (PMID 40421216, 2025). "Mechanistically, NLRP3 was shown to interact directly with the TGF-β receptor, promoting mothers against decapentaplegic homolog 3 (SMAD3) phosphorylation and facilitating Th17-to-Treg trans-differentiation within the tumor microenvironment." (PMID 41291696, 2025). "In vivo experiments further demonstrated that targeting the Smad3/CISD2 axis significantly suppressed xenograft tumor growth and activated ferroptosis." (PMID 41413023, 2025). "TGF-β1 activation and Smad3 phosphorylation promote tumor growth and metastasis, highlighting the importance of targeting TGF-β1 for therapeutic interventions." (PMID 39940962, 2025). "It has been reported that PRDM16 represses the transcriptional activity of TGF-β signaling and tumor cell proliferation by binding to p-Smad3 and suppressing the interaction of p-Smad3 with DNA." (PMID 40758676, 2025).
tumor (continued). "Through our stained and blotted OC cohorts, USP9X was parallelly expressed with p-Smad3 and positively correlated with tumor grading." (PMID 40246814, 2025). "Mechanistically, the development of MNT cells is predominantly regulated by the TGF-β1/Smad3 signaling pathway, and genetic ablation of Smad3 in macrophages markedly suppresses MNT formation and reduces tumor-associated pain behaviors." (PMID 41009819, 2025). "This unique pattern of SMAD3 expression and its functional consequences represent a significant departure from the mechanisms observed in tumor cells." (PMID 40721814, 2025). "ATRA notably increased Smad3 expression and showed at least partial reliance on Smad3, which was also observed in lewis tumor models." (PMID 41360769, 2025). "Immune cell infiltration levels, including CD4, CD8, FOXP3, CD163‐positive cells and expression levels of TGFβ1 and SMAD3 proteins in tumor tissue were evaluated by immunohistochemistry." (PMID 41187938, 2025). "In the present study, blocking of Smad3 signaling notably increased the production of GM-CSF by tumor-infiltrated NK cells, serving as a long-lasting source of GM-CSF in the tumor microenvironment." (PMID 38878186, 2024). "The only exception is cellular fibrous histiocytoma, which can closely resemble EWSR1::SMAD3-rearranged tumor morphologically and regularly show diffuse expression of ERG." (PMID 39264472, 2024). "Evidence suggests that inhibiting SMAD3 in CAFs diminishes its activation and secretion of extracellular matrix components, thereby curtailing tumor cell survival and enhancing radiosensitivity." (PMID 38493128, 2024). "This study also reveals high SMAD3 expression by CAFs within the tumor microenvironment, correlating with promoter hypermethylation." (PMID 38493128, 2024). "Linker phosphorylation–resistant mutation of Smad3 attenuates TGF-β–induced cell motility and in vivo tumor growth and metastasis." (PMID 38569937, 2024). "Protocadherin 1 (PCDH1), which binds to SMAD3 and acts as a tumor suppressor, was significantly upregulated (p < 0.0001 vs. ctrl)." (PMID 39054369, 2024). "Another important factor in tumor metastasis is SMAD3, which is involved in the activation of the transforming growth factor-beta (TGF-β) signaling pathway." (PMID 38415253, 2024). "Conversely, the tumor-suppressive miR-145 directly targets SMAD3, inhibiting TGF-β-induced EMT and metastasis in CRC." (PMID 38279330, 2024). "MiR-23a targeted and downregulated the SMAD3 signal, inhibiting tumor epithelial-mesenchymal transition and progression." (PMID 38362150, 2024). "These SMAD3 molecules are secreted into the tumor microenvironment and interact with ITGA6 on the membrane of NSCLC cells, resulting in its hyperactivation." (PMID 38493128, 2024). "In the HBx dysregulated HBV-HCC pathways, this panel of MIRNAs can influence a number of genes in the TGF-B/SMAD pathway by targeting validated gene targets like TGFBR1/SMAD3/, CDKN1A and MYC to influence both oncogenesis and the loss of tumor suppression." (PMID 38256049, 2024). "Mechanistically, the ADSCs-activated TGF-β1/SMAD3 signaling pathway transcriptionally upregulates the expression of ANGPTL4, which endows tumor cells with an invasive phenotype and is associated with a poor prognosis in CRC patients." (PMID 38643448, 2024). "Mechanically, circSLCO1B3 not only promoted ICC proliferation and metastasis via miR-502-5p/HOXC8/SMAD3 axis, but also eradicated anti-tumor immunity via suppressing ubiquitin-proteasome-dependent degradation of PD-L1 by E3 ubiquitin ligase SPOP." (PMID 38641828, 2024). "By Western blot analysis, at baseline, cultured tumor cells had low levels of p-SMAD3, which was upregulated by TGF-β and PGE2 incubation." (PMID 39298269, 2024). "The rest of the cells at the primary tumor site acquired several unique mutations (in genes SRC, SALL4, BAX, SMAD3), but with a slower mutation rate (PT2 PT3, PT5)." (PMID 38685065, 2024).
tumor (continued). "In this review, we focus on Smad2 function and its modulation by Smad3, which is often antagonistic to Smad2 in the context of tumor progression." (PMID 38569937, 2024). "Inhibiting Smad3 shifts neutrophils toward the anti-tumor N1 phenotype, enhancing tumor regression and suggesting Smad3 as a promising therapeutic target for cancer immunotherapy." (PMID 39759220, 2024). "Altogether, these results further supported the role of SMAD3 in controlling tumor recognition by NK cells through active cooperation with the epigenetic reader BRD4 in regulating inhibitory receptors and NK exhaustion genes." (PMID 38519469, 2024). "Existing studies have reported a TGF-β1–mediated association between SMAD3 and STAT3 in the regulation of hepatic or cardiac cell fibrogenesis, tumor cell fibrogenesis, and β cell dysfunction, cooperating with or antagonizing each other." (PMID 38441961, 2024). "KEGG pathway analysis indicates that the selected miRNA panel can specifically target SMAD3/CDKN1A/MYC in the TGF-B/SMAD pathway to influence tumor suppression and oncogenesis, as well as target CASP3 in the P13K/AKT pathway to influence apoptosis." (PMID 38256049, 2024). "SMAD3 up-regulated LINC09177 transcription by simultaneously binding the promoter and SE, which was induced by the infiltration of M2-like tumor-associated macrophages (TAM2), subsequently activating the TGF-β/SMAD3 pathway." (PMID 38566153, 2024). "Almost all of these entities can be distinguished from EWSR1::SMAD3-rearranged fibroblastic tumor based on typical morphological and immunohistochemical features." (PMID 39264472, 2024). "Research suggests that EVs from HCC cells can promote lung metastasis formation by regulating circulating tumor cells (CTCs) proliferation and adhesion by releasing SMAD family member 3 (SMAD3) protein." (PMID 39227992, 2024). "In this study, we identified the TGFβ/Smad3/MEN1 signaling axis as a potent tumor-suppressor pathway in cutaneous melanoma." (PMID 38891107, 2024). "These specific exosomes demonstrated anti-tumor properties by influencing the TGF-β/Smad3 pathway, inhibiting the proliferation and invasion of PCCs, and increasing apoptosis and cell cycle arrest." (PMID 38720811, 2024). "Overall, however, the evidence supports that Smad2 suppresses, whereas Smad3 promotes tumor development, malignant progression, and metastasis in several types of cancer, although the underlying mechanisms are divergent." (PMID 38569937, 2024). "Yet our data showed that blocking GM-CSF in Smad3 knockout NK cells significantly reduced the proportion of iNOS-producing M1 in tumor-infiltrated macrophages, illustrating that NK-derived GM-CSF exerts pro-inflammatory functions in the LLC microenvironment." (PMID 38878186, 2024). "Constructing a xenograft tumor mouse model, we found that SMAD3 knockdown significantly inhibited tumorigenesis." (PMID 38514720, 2024). "Silencing of SMAD3 enhanced NK cell development in mouse models and stimulated NK-dependent anti-tumor immunity." (PMID 38519469, 2024). "TGF-β exercises tumor resistance by promoting the transcription factors Smad2 and Smad3 to connect Smad4 to transmit signals." (PMID 38590651, 2024). "Meanwhile, MSP results showed that DNA methylation level of the promoter region of SMAD3 was decreased in tumor tissues compared with adjacent normal tissues." (PMID 38493128, 2024). "Collectively, our data suggest that the TGF-β1/SMAD3 axis is critical for the regulation of the anti-tumor activities of CD44+CD8+ T cells by CRC cell-expressed ATP6V0A1." (PMID 38971819, 2024). "Smad3’s function is determined by its phosphorylation status, with C-terminally phosphorylated Smad3 (pSmad3C) functioning as a tumor suppressor and linker-phosphorylated Smad3 (pSmad3L) contributing to oncogenesis." (PMID 38962270, 2024).
tumor (continued). "In this study, we observed the changes in the proportion of neutrophils in the tumor microenvironment by blocking Smad3 and GM-CSF in NK cells were comparable to those in the circulation." (PMID 38878186, 2024). "SMAD3 knockdown 4T1 cells were subcutaneously injected into mice to construct a xenograft tumor model in mice." (PMID 38514720, 2024). "Our study demonstrates a tumor-promoting role of SMAD3 in PCa cell growth dependent on the AR pathway." (PMID 36727462, 2023). "In summary, in this study, we define the role of Smad3 in the polarization of neutrophils within the tumor microenvironment." (PMID 37002229, 2023). "SMAD3 KD in Rv1 cells significantly decreased the frequency and size of xenograft tumor formation upon injection into athymic nude mice." (PMID 36727462, 2023). "In sum, these findings identify Smad3 as an immunoregulator that facilitates tumor growth via polarizing neutrophils towards an N2 phenotype within the TME." (PMID 37002229, 2023). "The activated TβRI can specifically recognize downstream Smad2 and Smad3, bind to and activate them, and the activated Smad2 and Smad3 dissociate from TβRI and then form heterologous complex with tumour suppressor gene Smad4." (PMID 37431884, 2023). "SMAD3 as a key modulator of “macrophage-to-neuron-like cell transition” promotion, which directly promoting tumor neurogenesis, representing a precision therapeutic target for cancer-related pain." (PMID 38022518, 2023). "It has been proved that ONECUT2 regulated the aggressive tumor biology in neuroendocrine prostate cancer through activating SMAD3-HIF1α signaling." (PMID 37444485, 2023). "It was found that among the tumour-associated neutrophils (TANs) from NSCLC patients, activation of SMAD3 in N2 TANs was negatively correlated with N1 numbers and patient survival." (PMID 37685308, 2023). "SMAD3 mRNA expression was low in 42.9% of Taiwanese CRC tumour tissues but high in 29.4% of tumours compared with paired adjacent normal tissues." (PMID 37685308, 2023). "The upregulation of SMAD3, which is part of the transcription factor complex and can serve as a tumor suppressor, has a similar effect." (PMID 37834191, 2023). "GADD45B-high tumor cells showed strong associations with transcription factors such as ELK1, PAX5, SMAD3, BACH1, and NR1H2." (PMID 37608794, 2023). "Given that the JICD1 transcriptional complex regulates cell migration and invasion via TWIST1, we investigated the functional consequences of JICD1/SMAD3-TWIST1-mediated cell migration on tumor aggressiveness in vivo." (PMID 38092725, 2023). "To further confirm that SCRN1 functions a tumor promoter in OSCC by regulating the TGF-β/Smad3 pathway, we next assessed the effects of TGF-β on OSCC cell proliferation, migration and invasion." (PMID 37691034, 2023). "An adoptive transfer approach was used as an additional strategy to examine how Smad3-KO and Smad3-WT neutrophils can affect tumor growth." (PMID 37002229, 2023). "Mechanistically, the tumour microenvironment induced SMAD3 expression to maintain the TAN in the N2 state." (PMID 37685308, 2023). "SMAD3 plays the dual role of oncogene and tumor suppressor gene in tumor formation, and can be used as a prognostic marker for tumors." (PMID 36969909, 2023). "The expression of CXCL8 was increased in CK7- and phospho-Smad3-positive acinar-type tumor tissue compared with solid-type tumor tissue in the A549 xenograft model, as well as in human LADC tissue and mutant KRAS-driven mouse lung cancer tissue." (PMID 37174001, 2023). "A functional role for these Smad3-KO N1 TANs in inhibiting tumor growth is confirmed by neutrophil depletion studies, while the adoptive transfer of Smad3-KO neutrophils inhibits tumor growth in wild-type mice." (PMID 37002229, 2023). "The stent protein PDLIM5 (PDZ and LIM structural domain protein 5, ENH) is a novel regulator of SMAD3 stability and critically promotes TGF-β signalling and tumour progression by maintaining SMAD3 stability in NSCLC." (PMID 37685308, 2023).